ERBB2 (erb-b2 receptor tyrosine kinase 2)
Diseases named in the same sentence as ERBB2 in open-access papers (continued):
Sharing a sentence is not in itself a finding about the gene and the disease.
hematological malignancies (31 papers, 2010 to 2025). "Analysis of the entire cohort of hematologic malignancies revealed 67 of 1348 cases (5.0%) harboring a rare germline ERBB2 coding variant, compared to 7 of 256 (2.7%) in the control cohort." (PMID 34209587, 2021). "Somatic mutations in ERBB2 are relatively common in many solid tumor malignancies; however, mutations in hematologic diseases are infrequent." (PMID 34209587, 2021). "Thus, we further investigated the ERBB2 gene as a candidate for germline predisposition to hematologic malignancy." (PMID 34209587, 2021).
CNS tumors (28 papers, 2014 to 2025). "The finding that merlin regulates SC NPC growth in a Rac1- and ErbB2-dependent manner firmly establishes a central growth control target for NF2-associated spinal ependymoma, and advocate for further studies addressing the potential use of ErbB2 inhibitors to treat these CNS neoplasms." (PMID 24817309, 2014).
benign tumors (21 papers, 2014 to 2025). "We were also able to uncover species-specific molecular characteristics, such as uncertain role for ERBB2 amplification in CMTs, and mutations prevalent in benign tumors that may reflect the early genetic basis underlining the initiation of CMT pathogenesis." (PMID 32680987, 2020).
gynecologic tumors (13 papers, 2016 to 2026). "Despite of the low prevalence of ERBB2 alterations in gynecological tumors, the good responses observed to these therapies warrant the need to determine this genomic aberration." (PMID 36010253, 2022).
hematological cancers (12 papers, 2012 to 2025). "By detecting the expression of kinases at the gene level in the PI3K/HDAC pathways with the CCLE database, we found that the expression levels of ErbB2 and ErbB3 in hematologic tumor cells were lower than those in solid tumors." (PMID 34658878, 2021). "The expression levels of ErbB2 and ErbB3 decreased in hematologic tumors compared with it in solid tumors." (PMID 34658878, 2021). "Therefore, we suggest that the efficacy of compound 23 against hematologic tumors may be related to the expression levels of ErbB2 and ErbB3 in hematologic tumor cells." (PMID 34658878, 2021). "Rituximab (a mAb specific to the B cell marker CD20), trastuzumab (anti-ErbB2/HER2 mAb) and cetuximab (an anti-EGFR mAb) have proved marked efficacies in the treatment of various solid and hematological tumors." (PMID 32272610, 2020). "Thus, the low expression of ErbB2 and ErbB3 stabilized the PI3K/Akt signaling pathway in hematologic tumors, thereby enabling compound 23 to exhibit more potent antitumor efficacy than against solid tumor cells." (PMID 34658878, 2021).
heart disease (11 papers, 2016 to 2025). "Thus it is likely that ErbB2/ErbB4 pathway is chronically activated in these conditions and its blockage by trastuzumab treatment may empathize trastuzumab-related cardiotoxicity in elder patients with undiagnosed heart diseases." (PMID 26836985, 2016).
head and neck tumors (7 papers, 2010 to 2024). "Aberrant activation of ERBB2 by gene amplification has been shown to participate in the pathophysiology of breast, ovarian, gastric, colorectal, lung, brain, and head and neck tumors." (PMID 23630663, 2013).
neurodegenerative disease (7 papers, 2014 to 2023). A disorder of the central nervous system characterized by gradual and progressive loss of neural tissue and neurologic function. "In recent years, increasing evidence has supported the role of the ERBB2 gene in the progression of many human degenerative diseases, including IDD." (PMID 37340393, 2023). "Combined with the expression levels in the brain and the supporting literature evidence related to neurodegenerative diseases in vivo and in vitro, we screened out FBXL20, PPP1R1B, NEUROD2 (NDF2), and ERBB2 (HER2) for follow-up molecular biology experiments." (PMID 35694256, 2022). "Observing levels of ERBB2 with respect to the PI3k-Akt and MAPK signaling pathway could elucidate its role in neurodegenerative diseases." (PMID 34379632, 2021). "Moreover, we found pathways that mediate fear conditioning and behavior signaling by ERBB2 (p = 0.00000711) and ERBB4 (p = 0.0000106), also involved in the development of neurodegenerative diseases." (PMID 33469418, 2020).
neurological disease (5 papers, 2019 to 2025). "In summary, glial NRG1-I/ErbB2-mediated paracrine and autocrine stimulation represents a novel neurological disease mechanism that constitutes an attractive target for therapeutic approaches of demyelinating peripheral nerve diseases." (PMID 30931926, 2019).
kidney disease (4 papers, 2013 to 2024). "Like CCND1, CTNNB1 and ERBB2 are also involved in numerous cellular functions and kidney disease." (PMID 23637735, 2013).
myopathy (2 papers, 2021 to 2025). A disease of the muscle in which the muscle fibers do not function properly. "Regarding the altered processes of cell communication, transcript abundance of the gene encoding for one of the epidermal growth factor receptors (EGFR) belonging to the ErbB family of receptor tyrosine kinases, ERBB2, was decreased for 1.5-fold in respect to WB myopathy." (PMID 34262480, 2021).
neurodevelopmental disorder (1 paper, 2025). A behavioral and cognitive disorder with onset during the developmental period that involves impaired or aberrant development of intellectual, motor, or social functions. "Dysregulation of ErbB2 signaling has been implicated in neurodevelopmental disorders, raising the possibility that ErbB2 may contribute more broadly to abnormalities in neural morphogenesis beyond the context of Sema5A mutations." (PMID 41226692, 2025). "Given that aberrant cytoskeletal remodeling is implicated in multiple neurodevelopmental disorders, these findings suggest that the ErbB2–Dock7 signaling axis may represent a common pathway through which distinct genetic alterations converge to produce similar cellular outcomes." (PMID 41226692, 2025).
ERBB2 also shares sentences with these, for which no sentence is quoted: carcinoma in situ (45 papers); gastrointestinal stromal tumor (39); neutropenia (39); Thrombocytopenia (35); metastatic melanoma (27); neuroendocrine tumors (27); lung squamous cell carcinoma (25); anemia (23); non-Hodgkin lymphoma (21); lobular breast cancer (20); Pleural effusion (20); chronic lymphocytic leukemia (19); Insulin resistance (19); cardiovascular disease (18); dyslipidemia (16); benign breast disease (15); Fibroadenoma (14); fibrosarcoma (14); astrocytoma (13); kidney cancer (13); prostate adenocarcinoma (13); Leptomeningeal Metastases (12); leukopenia (12); mesothelioma (12); mucinous adenocarcinoma (12); acute lymphoblastic leukemia (11); benign breast tumors (11); Ewing sarcoma (11); extramammary Paget disease (11); nasopharyngeal carcinoma (11).
A further 564 diseases each share a sentence with ERBB2 in 11 papers or fewer.